UBE2E1 (ubiquitin conjugating enzyme E2 E1)
Description:
Accepts ubiquitin from the E1 complex and catalyzes its covalent attachment to other proteins. Catalyzes the covalent attachment of ISG15 to other proteins. Mediates the selective degradation of short-lived and abnormal proteins. In vitro also catalyzes 'Lys-48'-linked polyubiquitination. Catalyzes monoubiquitination of other proteins in both an E3-dependent and E3-independent manner.
Synonyms: UBCH6
Tractability: Small molecule: a structure with a bound ligand is known. PROTAC: UniProt records ubiquitination sites on it; ubiquitination databases record sites on it; its protein half-life has been measured.
Target class: Enzyme; Transferase
Gene: Protein-coding gene on chromosome 3 (23,805,955 to 23,891,640, forward strand). Ensembl gene ENSG00000170142.
Subcellular location: Nucleus
Subcellular location (Human Protein Atlas): Nucleoplasm
Pathways (Reactome):
Cell Cycle: APC-Cdc20 mediated degradation of Nek2A; APC/C:Cdc20 mediated degradation of Cyclin B; APC/C:Cdc20 mediated degradation of Securin; APC/C:Cdc20 mediated degradation of mitotic proteins; APC/C:Cdh1 mediated degradation of Cdc20 and other APC/C:Cdh1 targeted proteins in late mitosis/early G1; Autodegradation of Cdh1 by Cdh1:APC/C; Cdc20:Phospho-APC/C mediated degradation of Cyclin A; Conversion from APC/C:Cdc20 to APC/C:Cdh1 in late anaphase; Inactivation of APC/C via direct inhibition of the APC/C complex; Phosphorylation of the APC/C; Regulation of APC/C activators between G1/S and early anaphase; Separation of Sister Chromatids
DNA Replication: Assembly of the pre-replicative complex; CDK-mediated phosphorylation and removal of Cdc6
Immune System: Antigen processing: Ubiquitination & Proteasome degradation; ISG15 antiviral mechanism
Metabolism of proteins: E3 ubiquitin ligases ubiquitinate target proteins; Synthesis of active ubiquitin: roles of E1 and E2 enzymes
Cellular responses to stimuli: Senescence-Associated Secretory Phenotype (SASP)
Disease: Aberrant regulation of mitotic exit in cancer due to RB1 defects
Gene expression (Transcription): Transcriptional Regulation by VENTX
Gene Ontology:
Molecular function: ISG15 transferase activity; protein binding; ubiquitin conjugating enzyme activity; ubiquitin-protein transferase activity
Biological process: ISG15-protein conjugation; positive regulation of transcription by RNA polymerase II; protein K48-linked ubiquitination; protein monoubiquitination; protein polyubiquitination; protein ubiquitination; ubiquitin-dependent protein catabolic process
Cellular component: nucleoplasm; nucleus; ubiquitin ligase complex; cytosol
Genetic constraint (gnomAD): Loss-of-function variants: 6 observed, 22.62 expected, observed/expected ratio (o/e) 0.27, 90% interval 0.14 to 0.52. The upper end of that interval is the gene's LOEUF score, 0.52, which puts it in group 2 of 6, group 1 being the genes least tolerant of losing a copy. Missense variants: 142 observed, 248.61 expected, observed/expected ratio (o/e) 0.57, 90% interval 0.5 to 0.66. Synonymous variants: 87 observed, 88.5 expected, observed/expected ratio (o/e) 0.98, 90% interval 0.83 to 1.17.
Homologues: Orthologues: chimpanzee UBE2E1 (100% identical), guinea pig UBE2E1 (100% identical), macaque UBE2E1 (100% identical), pig UBE2E1 (100% identical), mouse Ube2e1 (99% identical), rat Ube2e1 (91% identical). Paralogues in human: UBE2E2 (85% identical), UBE2E3 (82% identical), UBE2D2 (49% identical), UBE2D4 (49% identical), UBE2D3 (48% identical), UBE2D1 (47% identical), UBE2Q2 (28% identical), UBE2L6 (27% identical), UBE2Q1 (27% identical), UBE2L5 (27% identical), UBE2L3 (26% identical), UBE2QL1 (18% identical).
Diseases named in the same sentence as UBE2E1 in open-access papers:
UBE2E1 is named in the same sentence as 25 diseases in open-access papers, as found by Europe PMC text mining. Sharing a sentence is not in itself a finding about the gene and the disease. The quoted sentences say what the papers report.
acute myeloid leukemia (2 papers, 2016 to 2021). Acute myeloid leukemia (AML) is a group of neoplasms arising from precursor cells committed to the myeloid cell-line differentiation. "The UBE2E1 expression is adversely related to acute myeloid leukemia lifespan, though its role is unclear." (PMID 34769401, 2021). "UBE2E1 links with HOX gene regulation for its prognostic role in acute myeloid leukemia because HOX gene (HOXA9 and HOXA10) promotes acute myeloid leukemia leukemogenesis." (PMID 34769401, 2021).
frontotemporal dementia (2 papers, 2024 to 2025). Frontotemporal dementia (FTD) comprises a group of neurodegenerative disorders, characterized by progressive changes in behavior, executive dysfunction and language impairment, as a result of degeneration of the medial prefrontal and frontoinsular cortices. "Other UBE2 enzymes, such as UBE2I, UBE2Q1, UBE2E1, and UBE2Z, display varied regulatory patterns in neurodegenerative diseases like frontotemporal dementia, suggesting the Ube2 family’s extensive influence on neurodegeneration, inflammation, and cellular stress responses." (PMID 39108475, 2024).
liver cancer (2 papers, 2024 to 2025). An epithelial or non-epithelial malignant neoplasm that arises from the liver. "We propose that before the recognized oncogenic pathways are activated, four key DEGs (BMI1, NOP56, UBE2E1, and FAM98A) are aberrantly expressed, revealing the different prognoses of patients with liver cancer." (PMID 38515119, 2024).
Parkinson disease (2 papers, 2017 to 2025). A progressive degenerative disorder of the central nervous system characterized by loss of dopamine producing neurons in the substantia nigra and the presence of Lewy bodies in the substantia nigra and locus coeruleus. "On the other hand the decreased expression of ATPase and ubiquitin genes (ATP6AP2, UBE2e1, and Ube2q1) prevent mitochondrial oxidative stress leading to Parkinson's disease, Alzheimer's and X-linked mental retardation." (PMID 28423529, 2017). "Some studies have suggested that UBE2E1 may be involved in neurodegenerative diseases such as Alzheimer’s disease and Parkinson’s disease, and elevated levels of UBE2E1 may also be associated with inflammatory and autoimmune diseases." (PMID 41459514, 2025).
autoimmune disease (1 paper, 2025). A disorder resulting from loss of function or tissue destruction of an organ or multiple organs, arising from humoral or cellular immune responses of the individual to their own tissue constituents. "In particular, the strongest positive correlation was observed between Tfh and UBE2E1 (cor = 0.43, P < 0.01), suggesting that UBE2E1 may influence autoimmune diseases and inflammatory responses." (PMID 41459514, 2025).
endometrial cancer (1 paper, 2024). Primary or metastatic malignant neoplasm involving the endometrium (mucous membrane that lines the endometrial cavity). "NOP56 and UBE2E1 have been identified as molecular markers for endometrial cancer." (PMID 38515119, 2024).
Obesity (1 paper, 2024). Accumulation of substantial excess body fat. "Therefore, we subjected Ube2e2+/– Ube2e1+/– and Ube2e2+/+ Ube2e1+/+ control mice to diet-induced obesity." (PMID 39656538, 2024).
osteoporosis (1 paper, 2025). A condition of reduced bone mass, with decreased cortical thickness and a decrease in the number and size of the trabeculae of cancellous bone (but normal chemical composition), resulting in increased fracture incidence. "To date, no research has adopted a combined strategy of bioinformatics and experimental validation to jointly identify RPS27A and UBE2E1 as biomarkers related to ubiquitination in elderly osteoporosis." (PMID 41459514, 2025). "UBE2E1 may be involved in the occurrence and development of senile osteoporosis through the classical Wnt pathway." (PMID 41459514, 2025).
pancreatic cancer (1 paper, 2024). "Previously, UBE2E1 has been implicated in acute myelogenous leukemia (AML) and pancreatic cancer." (PMID 39057719, 2024).
uremia (1 paper, 2013). A clinical syndrome associated with the retention of renal waste products or uremic toxins in the blood. "However, probe sets of the protein-degradation machinery, e.g. UBE2E1, USP32, UBE2Q2, and UBR3 were inhibited in uremia, indicating that evaluation of the ubiquitin-proteosome machinery requires more detailed investigation." (PMID 23809614, 2013).
tumor (5 papers, 2008 to 2025). "We injected Huh7 cells with UBE2E1 knockdown into the subcutaneous space of NCG mice and observed a significant inhibition of tumor growth in vivo." (PMID 40740783, 2025). "Depletion of several ubiquitinases and proteasome components (DTX3L, UBE2E1, RNF31, RNF115, USP2, USP42, PSMC3, and PSMD10) were also found to inhibit tumor cell migration." (PMID 31278301, 2019).
infection (2 papers, 2013 to 2017). The state of being infected such as from the introduction of a foreign agent such as serum, vaccine, antigenic substance or organism. "In vitro, ICP0 is a biochemically active E3 ubiquitin ligase in the presence of E2 ubiquitin conjugating enzymes (E2s) [UBE2D1 (UbcH5a) and UBE2E1 (UbcH6)], but which E2s are used during infection has remained unclear." (PMID 23950709, 2013). "After retesting shRNAs targeting the top screen candidates, we found that infection with shRNAs targeting four of these genes (CDKN1A, MTOR, MYOT, and UBE2E1) resulted in a consistent bypass of OSKM-induced senescence." (PMID 29138277, 2017). "Depletion of UBE2D1-4, UBE2E1-3 and UBE2N significantly increased the number of PML-positive cells post-infection, in an ICP0-dependent manner, indicating that ICP0 can use multiple E2s to degrade PML." (PMID 23950709, 2013).
UBE2E1 also shares sentences with these, for which no sentence is quoted: neurodegenerative disease (3 papers); acute lymphoblastic leukemia (1); Alzheimer disease (1); bladder cancer (1); breast carcinoma (1); hematological malignancies (1); hepatoblastoma (1); leukemia (1); lymphoma (1); metabolic disease (1); osteosarcoma (1); rhabdomyosarcoma (1); Wilms tumor (1).